CD300E (CD300e molecule)
Description:
Probably acts as an activating receptor.
Synonyms: CLM-2; IREM-2; PIgR-2; PIgR2; CD300LE; CLM2; IREM2; CMRF35-A5
Tractability: Antibody: its Gene Ontology location is reachable by antibodies, with high confidence; UniProt places it where antibodies can reach, with medium confidence; UniProt predicts a signal peptide or a membrane-spanning region.
Gene: Protein-coding gene on chromosome 17 (74,609,878 to 74,623,738, reverse strand). Ensembl gene ENSG00000186407.
Subcellular location: Cell membrane
Pathways (Reactome):
Immune System: DAP12 interactions; Immunoregulatory interactions between a Lymphoid and a non-Lymphoid cell
Gene Ontology:
Molecular function: protein binding; transmembrane signaling receptor activity; cocaine binding
Biological process: regulation of innate immune response; signal transduction
Cellular component: plasma membrane; cell surface
Genetic constraint (gnomAD): Loss-of-function variants: 14 observed, 20.85 expected, observed/expected ratio (o/e) 0.67, 90% interval 0.44 to 1.05. The upper end of that interval is the gene's LOEUF score, 1.05, which puts it in group 4 of 6, group 1 being the genes least tolerant of losing a copy. Missense variants: 217 observed, 247.87 expected, observed/expected ratio (o/e) 0.88, 90% interval 0.78 to 0.98. Synonymous variants: 93 observed, 103.76 expected, observed/expected ratio (o/e) 0.9, 90% interval 0.76 to 1.07.
Homologues: Orthologues: chimpanzee CD300E (98% identical), macaque CD300E (90% identical), dog CD300E (59% identical), mouse Cd300e (56% identical), rat Cd300e (56% identical). Paralogues in human: CD300H (43% identical), CD300C (39% identical), CD300A (38% identical), CD300LD (37% identical), CD300LB (34% identical), CD300LF (30% identical), CD300LG (25% identical), FCMR (24% identical), TREM2 (24% identical), PIGR (23% identical), TREML1 (23% identical), FCAMR (22% identical), and 1 more.
Diseases named in the same sentence as CD300E in open-access papers:
CD300E is named in the same sentence as 23 diseases in open-access papers, as found by Europe PMC text mining. Sharing a sentence is not in itself a finding about the gene and the disease. The quoted sentences say what the papers report.
COVID-19 (3 papers, 2021 to 2023). A disease caused by infection with severe acute respiratory syndrome coronavirus 2. "Specifically, while the expression levels of CD300a and CD300e increased in monocytes from patients with mild and moderate disease, a drastic decrease was observed in patients with a severe form of COVID-19." (PMID 33777054, 2021). "It is interesting to see how the expression levels of an inhibitory receptor (CD300a) and activating receptor (CD300e) are regulated in the same manner in COVID-19 patients." (PMID 33777054, 2021). "Therefore, we decided to determine the expression of the inhibitory receptor CD300a and activating receptors CD300c and CD300e on monocytes from patients with COVID-19." (PMID 33777054, 2021).
Obesity (2 papers, 2022). Accumulation of substantial excess body fat. "With the present study, we investigated T-cell and antibody responses against CD300e, an antigen highly expressed in the adipose tissue of patients with obesity before the bariatric surgery-induced weight loss." (PMID 36419085, 2022). "Moreover, we evidenced in the sera of individuals with obesity an antibody response towards CD300e and revealed the existence of a significant correlation between the level of antibodies before surgery and the maintenance of glucose control after the intervention." (PMID 36419085, 2022).
Allergy (1 paper, 2022). An allergy is an immune response or reaction to substances that are usually not harmful. "Monocyte CD300e is a leukocyte mono-immunoglobulin-like receptor that recognizes lipids and is involved in allergy or inflammation." (PMID 34811710, 2022).
asthma (1 paper, 2023). "Therefore, subsequent studies must be conducted to validate the conjecture of CD300E as a diagnostic marker for asthma." (PMID 37259023, 2023). "We screened seven candidate diagnostic biomarkers for asthma using LASSO regression (namely, BCL10, CD300E, IER2, MMP13, OAF, TBC1D3, and TMEM151A), among which the area under the curve (AUC) value for CD300E and IER2 were 0.722 and 0.856, respectively." (PMID 37259023, 2023). "In the present study, we screened seven key genes using the LASSO algorithm and identified differentially expressed genes, namely, CD300E and IER2, with AUC values greater than 0.7 as diagnostic markers for asthma using ROC curve analysis." (PMID 37259023, 2023). "This study explored a potential lncRNA-miRNA-mRNA regulatory network and its underlying diagnostic biomarkers (CD300E and IER2) in asthma and identified the immune cells most associated with them, providing possible diagnostic markers and immunotherapeutic targets for asthma." (PMID 37259023, 2023). "Finally, we revealed the infiltration ratio of different immune cells in asthma and found a correlation between LUCAT1, MIR222HG, CD300E, and IER2 with some immune cells." (PMID 37259023, 2023). "Finally, we investigated the association between the immune cell ratio and the expression of LUCAT1, MIR222HG, CD300E, and IER2 in patients with asthma to determine the biomarkers correlated with the immune cell ratio." (PMID 37259023, 2023). "In this study, we screened key asthma-related genes (LUCAT1, MIR222HG, CD300E, and IER2) and immune cell infiltration profiles through bioinformatic analysis, which could provide insights into the pathogenesis of asthma and new perspectives and approaches for asthma diagnosis and treatment." (PMID 37259023, 2023). "Although CD300E and IER2 have not been reported in the context of asthma, CD300E serves as a biomarker for M2c macrophages." (PMID 37259023, 2023).
breast carcinoma (1 paper, 2024). "Additionally, our cellular experiments clearly demonstrate that the overexpression of CD300E in breast cancer cells is closely associated with enhanced cellular proliferation, reduced apoptosis rates, and increased migration and invasion capabilities." (PMID 39144140, 2024). "This study has identified CD300E as a critical target through gene sequencing of voluntary running wheel exercises in mice as an anti-breast cancer initiative." (PMID 39144140, 2024). "Notably, in cancers such as BRCA (Breast Cancer) and COAD (Colorectal Adenocarcinoma), a significant positive correlation exists between CD300E expression and M2 macrophages, typically associated with a tumor-promoting immunosuppressive environment." (PMID 39144140, 2024). "Experiments aimed at inhibiting CD300E expression further validate its significant role in tumor cell proliferation and survival, offering a potential therapeutic strategy to curb the progression of breast cancer." (PMID 39144140, 2024). "Additionally, exercise appears to inhibit breast cancer progression potentially by downregulating CD300E." (PMID 39144140, 2024). "Compared to control cells, overexpression of CD300E in MDAMB468 and MDAMB231 breast cancer cells leads to increased proliferation and cell viability, while suppression of CD300E expression reduces proliferation and cell viability." (PMID 39144140, 2024).
chronic gastritis (1 paper, 2017). Inflammation of the stomach that is chronic in nature. "Macrophages expressing CD300E accumulates in the gastric mucosa of Hp-infected subjects with chronic gastritis while its expression drops down upon bacteria eradication." (PMID 29085364, 2017). "Notably, CD300E is not appreciable in the gastric mucosa of Hp-negative chronic gastritis, hence its upregulation can be considered a hallmark of Hp infection." (PMID 29085364, 2017).
Cirrhosis (1 paper, 2025). A chronic disorder of the liver in which liver tissue becomes scarred and is partially replaced by regenerative nodules and fibrotic tissue resulting in loss of liver function. "Our findings demonstrated that CD300E+ macrophages play a crucial role in remodeling the hepatic immune microenvironment after splenectomy, thereby promoting liver regeneration in patients with decompensated cirrhosis." (PMID 39741181, 2025). "Therefore, CD300E+ MDMs regulate the energy metabolism of hepatocytes by secreting NAMPT, which may be the intrinsic mechanism of hepatocyte proliferation after splenectomy in patients with cirrhosis." (PMID 39741181, 2025).
colorectal cancer (1 paper, 2024). A primary or metastatic malignant neoplasm that affects the colon or rectum. "For instance, in breast and colorectal cancers, Cancer-associated fibroblasts (CAFs) show a strong positive correlation with CD300E expression, suggesting their significant role in supporting or enhancing tumor growth and invasion, closely linked with the expression of this gene." (PMID 39144140, 2024). "Expanding our analysis to a broader cancer spectrum, CD300E demonstrated significant expression variability across multiple cancer types, with pronounced upregulation in myeloma, ovarian, lung, and colorectal cancers." (PMID 39144140, 2024). "Notably, CD300E is upregulated in cancers such as Myeloma, Diffuse Large B-cell Lymphoma, Ovarian Cancer, Lung Cancer, and Colorectal Cancer, suggesting its involvement in the progression of these diseases." (PMID 39144140, 2024). "The Human Atlas database further assessed the protein expression of CD300E across various cancers, showing upregulation in Myeloma, Diffuse large B-cell lymphoma, Ovarian cancer, Lung cancer, and Colorectal cancer without significant downregulation in any cancer type." (PMID 39144140, 2024).
diabetes (1 paper, 2016). "Taken together, CD300e is suggested to play a role in the initiation of beta cell destruction, which is followed by the preclinical stage for a few weeks, resulting finally in overt diabetes in FT1D." (PMID 27513516, 2016).
gastritis (1 paper, 2017). Inflammation of the stomach. "The accumulation of CD300E+ macrophages strictly relies on the presence of the bacterium, since they were virtually absent in patients that underwent Hp eradication as well as in patients with Hp− (negative) gastritis." (PMID 29085364, 2017).
liver cirrhosis (1 paper, 2025). "CD300E+ macrophages are anticipated to emerge as a novel therapeutic strategy for the treatment of liver cirrhosis." (PMID 39741181, 2025).
lung adenocarcinoma (1 paper, 2024). A carcinoma that arises from the lung and is characterized by the presence of malignant glandular epithelial cells. "Conversely, in Lung Adenocarcinoma (LUAD), CD300E exhibits a negative correlation with natural killer (NK) cells, although this association generally lacks statistical significance." (PMID 39144140, 2024).
pancreatic cancer (1 paper, 2017). "CD300E is expressed at low level in muscle, lung, kidney, and adipose tissue, whereas it is upregulated in different cancers, namely, colorectal, stomach, liver, ovarian, and pancreatic cancer." (PMID 29085364, 2017).
cancer (5 papers, 2017 to 2024). A tumor composed of atypical neoplastic, often pleomorphic cells that invade other tissues. "Prognostic analyses reveal that CD300E acts as a risk factor in several cancers, providing valuable insights that may guide clinical prognostic assessments and therapeutic decision-making." (PMID 39144140, 2024). "Moreover, CD300E expression was associated with cancer cell proliferation and apoptosis." (PMID 39144140, 2024). "mRNA sequencing post-exercise revealed substantial downregulation of CD300E in the exercise group, accompanied by alterations in critical pathways such as MicroRNAs in cancers and the Calcium signaling pathway." (PMID 39144140, 2024). "Bar graphs showed changes in CD300E copy numbers across various cancers, with significant variations in KICH and READ." (PMID 39144140, 2024). "The study highlights the dual role of exercise in modulating gene expression relevant to tumor growth and the potential of CD300E as a target in cancer therapeutics." (PMID 39144140, 2024). "This research not only sheds light on the mechanistic underpinnings of CD300E in cancer biology but also underscores the potential of exercise-induced molecular responses as a strategic approach in cancer prevention and treatment." (PMID 39144140, 2024). "In our pan-cancer analysis, CD300E exhibits significant expression variability across multiple cancer types, underscoring its potential role in various malignancies." (PMID 39144140, 2024). "Promoter methylation, a critical epigenetic regulatory mechanism affecting gene expression without altering the DNA sequence, was analyzed to explore its relationship with CD300E expression across multiple cancer types." (PMID 39144140, 2024). "Further mechanistic studies should delve into how CD300E activates or inhibits cancer-related pathways, particularly how it influences key tumor behaviors such as cell cycle progression, apoptosis, migration, and invasion." (PMID 39144140, 2024). "Further analysis using the TCGA database’s pan-cancer dataset revealed a broadly positive correlation between CD300E and various immune cells across different cancer types." (PMID 39144140, 2024). "This research explored the impact of exercise on tumor growth and gene expression within a murine model, focusing particularly on the expression patterns, functions, and potential clinical significance of the CD300E gene across various cancers." (PMID 39144140, 2024). "Our further evaluation of CD300E’s function in pan-cancer contexts revealed significant findings via the GSEA methodology." (PMID 39144140, 2024). "Future research should further explore the specific molecular mechanisms of CD300E and its role in different cancers to advance the development of novel anti-cancer strategies." (PMID 39144140, 2024). "Further in-depth evaluation using RNA-seq data from TCGA and GTEx databases revealed significant expression differences in CD300E across 33 types of cancer." (PMID 39144140, 2024). "In unmatched samples, CD300E was notably upregulated in cancers like BRCA, COAD, ESCA, GBM, HNSC, KIRC, and STAD, and downregulated in KICH, LIHC, LUAD, LUSC, and PAAD." (PMID 39144140, 2024). "Sub-cluster 15–4 is likely to be related to the function of monocyte CD300e and cancer ARID1A genes, which have recently attracted much attention." (PMID 34811710, 2022). "These PSRs including BAI1, CD300e, Stabilin-1 and others are worth considering in the context of anti-cancer immune therapy." (PMID 32087708, 2020). "Overall, targeting CD300E could directly inhibit tumor cells, significantly impeding cancer progression and presenting a novel therapeutic target." (PMID 39144140, 2024). "Furthermore, our analysis elucidates the role of CD300E in regulating key signaling pathways related to cancer progression, especially in suppressing oxidative stress pathways and activating several pathways that promote tumor progression." (PMID 39144140, 2024).
cancer (continued). "Our findings indicate that CD300E may adversely affect prognosis and promote tumor progression across a range of cancers." (PMID 39144140, 2024). "In summary, CD300E not only plays a potentially crucial role in the process of exercise-mediated tumor growth inhibition but also exhibits viability as a therapeutic target based on its expression and function across various cancers." (PMID 39144140, 2024). "These mutations may affect cell cycle regulation, DNA repair mechanisms, and pathways of cell death, further substantiating the potential role of CD300E in pan-cancer contexts." (PMID 39144140, 2024). "Further research is encouraged to explore the mechanisms by which exercise and CD300E influence cancer progression and to develop targeted strategies that could enhance patient outcomes in clinical settings." (PMID 39144140, 2024). "This trend implies that in certain cancer contexts, CD300E expression may inversely affect the immunosurveillance capabilities of NK cells, potentially contributing to mechanisms of immune escape." (PMID 39144140, 2024). "It is also suggested that monocyte CD300e and cancer ARID1A gene in sub15-4 (2020) may also be candidate topics that continue to follow." (PMID 34811710, 2022). "Additionally, investigating the role of CD300E across different cancers and immune backgrounds may reveal its multifunctional potential as a therapeutic target." (PMID 39144140, 2024). "In addition, one patent have reported that CD300E siRNA delays or halts cancer progression by blocking or knocking down cd300e to inhibit its activity or expression, and that the rate of tumor growth is significantly inhibited in mouse tumors compared to controls." (PMID 39144140, 2024). "Moreover, in cancers like LUAD, the activity of CD8+ T cells significantly correlates with CD300E expression, reflecting their importance in the tumor immune response and the potential regulatory role of this gene." (PMID 39144140, 2024). "Additionally, in certain cancer types like BRCA, CD300E shows a positive correlation with regulatory T cells (Tregs), which play a critical role in modulating the immune system, particularly in maintaining immune tolerance and suppressing excessive immune responses." (PMID 39144140, 2024).